GPC3 (glypican 3)
Diseases named in the same sentence as GPC3 in open-access papers (continued):
Sharing a sentence is not in itself a finding about the gene and the disease.
tumor (continued). "Since E-Cadherin suppression in cancer cells enhances the development of migratory and invasive phenotype and facilitates dissociation from the surrounding extracellular matrix of the primary tumor site, we suggest that GPC3 would induce MET by regulating E-Cadherin expression." (PMID 27507057, 2016). "Furthermore, we found a correlation between GPC3 expression rate and vascular invasion, >50% tumor involvement in the liver, lymph nodes involvement, alcohol use, cigarette smoking, race, gender, age, or stage (CLIP, TNM, BCLC and CTP)." (PMID 27655712, 2016). "The results of these experiments demonstrated that the CARgpc3 T cells could effectively target and remove GPC3-positive tumor cells in vivo." (PMID 26684028, 2016). "Downregulated expression of GPC3 in HCC cells may affect GPC3-CAR T-specific cytotoxicity to tumor cells." (PMID 28123387, 2016). "This would be in line with the known expression of glypican-3 or AFP in these tumours." (PMID 25889715, 2015). "Although vaccine-induced GPC3-peptide-specific cytotoxic T lymphocytes (CTLs) are often tumor reactive in vitro and correlate with overall survival, no complete response was observed when GPC3 peptide vaccination was used as monotherapy in patients with advanced HCC." (PMID 25354479, 2015). "Furthermore, HepG2-induced tumor growth in vivo was found to be effectively inhibited by DCs-GPC3-CIKs." (PMID 25625609, 2015). "Four studies reported data on GPC3 expression and tumor multifocality in HCC." (PMID 24548704, 2014). "In addition, the correlation between GPC3 expression and tumor pathological features (such as tumor grade, stage, or vascular invasion) was also examined." (PMID 24548704, 2014). "Four studies reported data on GPC3 expression and tumor size ≥ 5 cm in HCC." (PMID 24548704, 2014). "Four studies also provided data on the correlation of GPC3 with tumor TNM stage." (PMID 24548704, 2014). "In order to confirm this hypothesis, we analyzed tumor infiltrating CD8+T cells and found infiltrating CD8+T cells increase in GPC3-expressing tumor." (PMID 24992906, 2014). "The relation between GPC3 and tumor pathological features was also assessed." (PMID 24548704, 2014). "GPC3 would be a more reliable tumor marker that could allow an earlier diagnosis of HCC when compared with serum alpha-fetoprotein." (PMID 24548704, 2014). "Additionally, replating assays and immunocytochemical analyses of EpCAM and AFP indicated that GPC3 regulated tumor-initiating HCC cells." (PMID 24454751, 2014). "An increased number of CD86+ macrophages were present in the GPC3-expressing tumor." (PMID 24992906, 2014). "The role of glypican 3 as a tumor marker needs further clinical evaluation." (PMID 23688193, 2013). "GPC-3, a membrane-bound heparan sulfate proteoglycan that is overexpressed in most HCCs, promotes the tumor growth by stimulating Wnt signaling, because GPC-3 binds with high affinity to Wnts and its growth-promoting activity requires attachment to the cell membrane." (PMID 23192642, 2013). "It was reported that to some extent, high-sensitivity AFP-L3, AFP-IgM complex, calcium, GP73, DCP bursin, VEGA, GPC-3, and other markers can improve the sensitivity for detection of tumor recurrence in AFP-negative HCC, and have predictive value for the HCC therapeutic effect." (PMID 23981851, 2013). "Specific shRNA might intervene effectively GPC-3 activation and inhibit tumor cell proliferation, suggesting that GPC-3 gene should be a potential molecular target for HCC therapy." (PMID 23192642, 2013). "Meanwhile, low GPC3 staining combined with positive serum AFP may play a practical role in predicting poor postoperative outcome and high tumor recurrence risk." (PMID 23537217, 2013). "It was difficult to confirm that these tumor-infiltrating CD8+T cells have specificity for GPC3." (PMID 23903757, 2013).
tumor (continued). "In addition, age, HBsAg, serum AFP, TNM, and tumor differentiation differed significantly between GPC3-low and GPC3-high patients, and these results were similar to those from previous reports." (PMID 23537217, 2013). "BALB/c nude mice were inoculated subcutaneously on their backs with SW620 (GPC3−) tumor cells." (PMID 23143746, 2013). "Furthermore, some other tumor markers, such as GPC3, GGT II, AFU, have been shown to be supplementary to AFP and DCP in the detection of HCC." (PMID 22655201, 2012). "Finally, Ccnd1, Gpc3, Mvk, Pparg, Rbl2, and Robo1 exhibited a tumor-specific response, where adverse expression changes were observed for Pparg, which appeared down regulated in transgenic cells (fold change <0.4) and significantly up regulated in tumors." (PMID 21464922, 2011). "Thus, based on the tumor cells positive reactivity for GPC3, AFP, hepatocyte antigen, Hep Par 1, and CK18, we thought that the seminal vesicle mass should firstly be considered as a metastatic HCC lesion." (PMID 21443783, 2011). "Further studies are required to investigate whether anti-GPC-3 immunotherapy has a role in the treatment of GPC-3 dependent tumours, such as HCC." (PMID 20465843, 2010). "GPC-3 appears to be an eminently suitable target molecule for HCC immunotherapy because it is a foetal protein that is expressed early in the development of HCC and has been implicated directly in tumour progression." (PMID 20465843, 2010). "Additionally, 7 genes known to possess tumor suppressor function (e.g. GPC3/OCI-5, LOT1/PLAGL1/ZAC1, etc) were down-regulated by MEK-activation." (PMID 17112382, 2006). "Interestingly, we found that NK92MI/HN3 cell showed different killing activities to different HCC cells, indicating that GPC3 isoform existence may have potential impact on anti-tumor efficiencies." (PMID 39841705, 2025). "GPC3 elevation can be detected in about 50–60% of AFP-negative HCC patients, which may be related to its specific activation in dedifferentiated tumor cells, while elevated DCP is caused by defective carboxylation of specific amino-terminal glutamic acid residues in HCC patients." (PMID 41471145, 2025). "Loading tumor cell membrane, chitosan, exocrine, GPC3, and other biocompatible substances can improve the biocompatibility of curcumin nanoparticles and have the ability of tumor-targeting, which could effectively play an antitumor role in prostate cancer, liver cancer, and other tumors." (PMID 38918994, 2025). "Although GPC3 expression was significantly associated with poor overall survival in advanced (stage III/IV) OCCC, there was a negative correlation between GPC3 expression and clinicopathological aspects, such as tumour stage, lymph node spread peritoneal metastasis, and death rate." (PMID 36768291, 2023). "This suggested that GPC-3 could serve as a tumor biomarker for HCC." (PMID 36850982, 2023). "Under the guidance of the surface-modified aptamer, the G-NK cells could bind to GPC3+ tumor cells and subsequently trigger cell apoptosis and necrosis in vitro, leading to enhanced immunotherapeutic efficiency in vivo after enrichment at the tumor site." (PMID 37665421, 2023). "These tumor antigens are the primary targets used in ACT for HCC and mainly fall into one of the three categories, including tumor-associated antigens (e.g., AFP, GPC-3), viral-derived cancer antigens (VHB, VHC), and cancer–testis antigens (e.g., NY-ESO-1, MAGE)." (PMID 36980692, 2023). "The results revealed that AFP>10 ng/ml, tumor size>3.0 cm, nonperipheral “washout”, infiltrative appearance, marked diffusion restriction, and iron sparing in solid mass were significantly associated with GPC-3 positive expression." (PMID 36091074, 2022). "We observed that CAR (GPC3) T cells killed Hep3B tumor cells efficiently but inducible PD-L1 expression was found in the Hep3B cells co-cultured with CAR (GPC3) T cells rather than control CAR (CD19) T cells, which may allow cancers to evade the host immune system." (PMID 35317524, 2022).
tumor (continued). "Furthermore, GPC3 could promote the progression and metastatic spread of HCC by influencing the functioning of tumor-associated macrophages (TAM) through macrophage recruitment." (PMID 35251989, 2022). "Based on tissue type, GPC3 may serve as an oncofetal protein or a tumour-suppressor protein." (PMID 36676710, 2022). "However, despite its strong affinity for GPC-3, the antibody’s large size may have adverse consequences, including inadequate imaging pharmacokinetics, poor tumor penetration, and higher immunogenicity." (PMID 35624643, 2022). "Furthermore, by tail vein injection, the elevated tumor metastasis could be softened by miR-4510 inhibition + GPC3-shRNA, suggesting that the function of miR-4510 relied on GPC3." (PMID 35050429, 2022). "In comparison with the CD19 control, no GPC3 loss was found in the tumor treated with GPC3 CAR." (PMID 35317524, 2022). "The proportion of EPCAM+ or GPC3+ cells was relatively stable in the tumor core regions while differences were noted when compared to the tumor border regions, suggesting that the proportion of those cells may vary among tumor regions." (PMID 36476645, 2022). "Glypican-3 (GPC3) is a promising therapeutic target for HCC because high expression of GPC3 is associated with advanced HCC, high tumor grade, vascular invasion, short survival, and poor prognosis, and immunohistochemical GPC3 reactivity reflects tumor staging." (PMID 33859758, 2021). "We also assessed the expression level of glypican-3 (GPC3), a biomarker for diagnosis and prognosis of HCC, to address whether Pgrmc1 modulates HCC malignancy in vivo, and found that the GPC3 expression level in the tumor regions was comparable between WT and Pgrmc1-null livers." (PMID 34069911, 2021). "In addition, there are a variety of novel serological molecular markers under exploration such as glypican-3, Golgi protein 73, α-L-fucosidase, osteopontin, microRNA, circulating tumor cells, circulating tumor DNA, exosomes, and circulating tumor DNA methylation." (PMID 34846705, 2021). "In addition, the three-gene risk-score model (involving MFI2, FOXM1, and GPC3) for LUAD and the two-gene risk-score model (involving SERPINA1 and FOXM1) for LUSC might be useful in predicting the prognosis of tumour patients." (PMID 34112123, 2021). "F3 peptide could successfully distinguish GPC-3 in different cell lines and human tumor samples." (PMID 34150644, 2021). "This enhanced tumor growth delay in animals treated with either amount of [225Ac]Ac–Macropa–GC33 compared to [225Ac]Ac–Macropa–IgG1 is supported by biodistribution data confirming the ability of [225Ac]Ac–Macropa–GC33 to preferentially target GPC3 in vivo in the HepG2 tumor model." (PMID 33374953, 2020). "Additionally, the level of E-cadherin was low in GPC3 overexpressing HCC tumor tissues." (PMID 33643907, 2020). "Responses elicited by GPC3-CIRP vaccine not only recognized synthetic 522–530 peptide but could also detect the naturally processed epitope presented by tumor cells, since they were activated by B16F10 tumor cells expressing HLA-A2*01 and GPC3, but not by parental B16F10 cells." (PMID 33207844, 2020). "Furthermore, patients with cancers positive for both antigen proteins, i.e., HSP70 and GPC3, tended to present a better overall survival (P = 0.08) and that tumor markers were reduced more often in patients with peptide-specific CTL induction for at least one of the two peptides (P = 0.031)." (PMID 32219501, 2020). "In addition, plasma levels of GPC3 have been suggested to predict HCC tumor recurrence." (PMID 32443747, 2020). "Therefore, GPC3 may play different roles in different tumor microenvironments, and its biological function may be highly related to the molecular composition in the microenvironment in which it is located." (PMID 32127929, 2020).
tumor (continued). "To test whether the toxicity that may result from GPC3-synNotch-inducible CD147-CAR targeting of CD147 in healthy tissues, we generated a hCD147TG mouse model to test the on-target/off-tumor toxicity of GPC3-synNotch-inducible CD147-CAR-NK-92MI treatment of HCC." (PMID 32968061, 2020). "Frequency of GPC3 positivity in tumoral tissues was recorded as 73.3% (33 cases) which wassignificantly higher than non-neoplastic tissues (p< 0.001).The clinicopathologic features of GPC3 expression demonstrated no associationwith clinicopathologic parameters except tumor size." (PMID 32582830, 2020). "Thus, we conclude that these activated GPC3-synNotch-inducible CD147-CAR-NK-92MI cells do not cause severe on-target/off-tumor toxicity in vivo." (PMID 32968061, 2020). "In addition, we found that GPC3 would be a promising tumor marker for diagnosing N-HCC." (PMID 31635078, 2019). "On the other hand, the mechanism underlying the expression of GPC3 in HCCs is not well understood; however, considering the reciprocal interaction of MCT4 and GPC3, GPC3 expression might also be regulated by a hypoxic tumor microenvironment, which could decrease GPC3 expression in HCC cells." (PMID 31706332, 2019). "In this study, we examine this theory using data from a randomized phase II clinical study to determine whether the combination of GPC3 expression in tumor and CD16 expression on NK cells in peripheral blood can be used as useful biomarkers to identify responders to codrituzumab versus placebo." (PMID 29535817, 2018). "Therefore, GPC3 expression in the primary tumor could be used as a biomarker to determine the efficacy of GPC3-derived peptide vaccines." (PMID 30297672, 2018). "The results showed that CK19/GPC3 expression pattern [hazard ratio (HR)=1.782, 95% confidence interval (CI)=1.137–2.793, P=0.012], histological grading (HR=1.969, 95%CI=1.292–3.001, P=0.002) and tumor number (HR=2.173, 95%CI=1.328–3.557, P=0.002) were the independent predictors of RFS." (PMID 28968990, 2017). "Furthermore, livers from rats transplanted with sheets fabricated from HepG2 –BM-MSCs or HepG2 alone showed increased expression of GPC3, the early diagnostic tumour marker while the livers of rats transplanted with HepG2 –UC-MSCs showed no expression of GPC3." (PMID 28850615, 2017). "This might be because GPC3 immunoreactivity was affected by the tumor differentiation grade." (PMID 29152084, 2017). "It is likely that GPC3-CAR T cells may kill tumor cells in synergy with mouse NK cells." (PMID 28123387, 2016). "Additionally, a much higher number of CAR-GPC3 T cells might persist in the peripheral blood and infiltrate the tumor tissues compared with other control T cells, which suggests that GPC3-targeting is important for the activation and expansion of CAR T cells." (PMID 26684028, 2016). "Targeting the HS chains of GPC3 could inhibit HCC tumor pathogenesis through multiple mechanisms." (PMID 26332121, 2015). "In addition to the current data, several similarities with the human pattern of HCC have been shown in our model, by the positive staining for p-AKT, p-c-Myc and Glypican-3 distribution observed in the tumor parenchyma of mice treated for 9 months with CDAA and CCl4." (PMID 24853141, 2014). "Consequently, we found GPC3 expression increases apoptotic cells in tumor masses." (PMID 24992906, 2014). "It is worth noting that, in this work, we report a decrease in the expression of GPC1 and an increase in GPC5 with increasing tumor grade, suggesting that the involvement of these molecules in cancer, as in the case of GPC3, may range from tumor suppressors to oncogenes depending on tumoral context." (PMID 24570896, 2014). "GPC3 expression could be involved in the aetiology of embryonal tumours such as NB and WT." (PMID 15083193, 2004). "•New agents are in development targeting Wnt/β-catenin, GPC-3, the FGF19-FGFR4 axis, and the tumour microenvironment." (PMID 41503573, 2026).
tumor (continued). "In multivariate analysis adjusted for age, sex, tumor stage (BCLC) and HCC treatment, GPC-3 > 150 pg/mL remained an independent predictor of poorer survival (aHR = 1.68, 95% CI 1.03–2.67, p = 0.036)." (PMID 41511652, 2026). "Taken together, these data suggest that elevated serum GPC-3 may reflect not only tumor presence but also a more aggressive biological phenotype, thus offering a plausible explanation for the worse prognosis observed in patients with high GPC-3 circulating levels." (PMID 41511652, 2026). "The involvement of GPC-3 in key oncogenic pathways, such as Wnt, YAP, and Hedgehog, suggests that it plays a role in tumour growth and metastasis, making it a promising candidate for targeted therapy." (PMID 41503573, 2026). "In the tumor lesion, a malignant STMN1+HMGN2+GPC3+ cell subtype enriched in MVI+ HCC was identified, which exhibited enhanced proliferative activity and was associated with poor prognosis." (PMID 42139279, 2026). "The GPC3-targeted peptide vaccine induces a CTL response, leading to decreased tumor markers and extended survival in some patients;DC vaccines demonstrate good safety and some efficacy in early HCC trials." (PMID 40568600, 2025). "In previous experiments, a construct known as Ad5f35-anti-GPC3-CAR, which utilized a chimeric adenoviral vector (Ad5f35), demonstrated impressive antigen-specific phagocytosis and tumor cytotoxicity." (PMID 40308592, 2025). "Researchers found that cross-linking T cells with GPC3-positive tumor cells with a GPC3/CD3 bsAb mediated potent GPC3-dependent and concentration-dependent cytotoxicity in vitro and significantly inhibited tumor growth in murine xenograft models." (PMID 39858016, 2025). "Targeting strategies, including GPC3, ASGPR1, LDL receptors, and GLUT1 transporters, improve cellular uptake, therapeutic efficacy, and tumor-specific accumulation." (PMID 40278256, 2025). "HCC patients’ GPC3 levels were further analyzed based on age, gender, CHILD grade and clinical characteristics of the tumor." (PMID 41471145, 2025). "EZH2, AURKB, GPC3, CTNNB1, and TGFβ were significantly upregulated in tumor tissues, indicating their potential roles in tumor progression." (PMID 40766612, 2025). "Examples include NPs with GPC-3 antibodies, which are abundant in PLC, and platelet-loaded levantinib/sorafenib that adheres to tumor blood vessels and tumor-circulating cells, therefore increasing accumulation at those sites." (PMID 40278256, 2025). "Combining GPC3 with EGFR, third-generation GPC3-EGFR CAR-T cells have been designed, showing enhanced proliferation and cytotoxicity while minimizing non-tumor toxicity." (PMID 40303292, 2025). "In Glypican-3 (GPC3)-targeted CAR-T cells, SATB1 was significantly downregulated in tumor-infiltrating exhausted populations." (PMID 41372119, 2025). "Recent clinical trials have demonstrated that ADCs targeting GPC3, such as GC33 and 32A9, show promising results in reducing tumor growth and improving patient outcomes in advanced HCC." (PMID 40416124, 2025). "For example, anti-GPC3 antibodies, which target glypican-3 (GPC3), a cell surface glycoprotein overexpressed in HCC, can induce ADCC, leading to tumor cell lysis." (PMID 40621467, 2025). "In contrast, a GPC3-specific MRI probe comprising the currently used Gd contrast agent may be more readily integrated into clinical workflows and may even be used in combination with functional MRI techniques to provide a comprehensive assessment of tumor biology." (PMID 41154412, 2025). "Current investigations into Glypican-3, a highly specific antigen in HCC, have demonstrated that BsAbs targeting both Glypican-3 and CD3 can significantly enhance cytotoxic immune responses against tumor cells." (PMID 40918452, 2025). "GPC3-targeted CAR-NK cells have demonstrated strong antitumor activity in vitro and in animal models, effectively infiltrating tumor sites, reducing proliferation` and inducing apoptosis." (PMID 40705122, 2025).